TNF (tumor necrosis factor)
Diseases named in the same sentence as TNF in open-access papers (continued):
Sharing a sentence is not in itself a finding about the gene and the disease.
cerebral malaria (continued). "In particular, the balance of inflammatory Type I cytokines, such as interferon gamma (IFNG) and tumour necrosis factor (TNF), with Type II cytokines, e.g., interleukin 4 (IL4) and IL10, is thought to determine the lethality of cerebral malaria." (PMID 25192715, 2014). "Evidence from both an experimental cerebral malaria (ECM) model, as well as from SM patients, have identified TNF as an important pro-inflammatory cytokine for the control of infection, and also a strong association with the development of pathology." (PMID 21029472, 2010). "Another study reported that patients with HIV and cerebral malaria have lower median plasma levels of TNF-α and IL-10 than patients without HIV." (PMID 36692923, 2023). "We have included studies of P. falciparum-infected humans with or without cerebral malaria and TNF-α dosage level." (PMID 32576141, 2020). "Also, circulating serum P. falciparum MIF levels positively correlated with serum TNF-α levels in malaria patients, and higher P. falciparum MIF levels were observed in patients with severe malarial anemia and cerebral malaria." (PMID 31497025, 2019). "This is probably because the TNF-α is a key cytokine in cerebral malaria and probably the patients we examined that time none had cerebral malaria." (PMID 29560020, 2018). "Using the blood-stage PbA (Plasmodium berghei ANKA) model of infection, we show here that administration of the pro-Th2 cytokine, IL-33, prevents the development of experimental cerebral malaria (ECM) in C57BL/6 mice and reduces the production of inflammatory mediators IFN-γ, IL-12 and TNF-α." (PMID 25659095, 2015). "Caution is required here since a trial in the Gambia of monoclonal antibody to TNF-α for children with cerebral malaria resulted in no improvement in survival and an increase in neurological sequelae." (PMID 26581890, 2015). "Furthermore, ICAM-1 expression by endothelial cells is enhanced by TNF-α and IL-1β, and ICAM-1 is important in cell adhesion, including adhesion of PRBC, in models of cerebral malaria." (PMID 23300448, 2012). "TNFα can increase platelet binding to the brain microvasculature in ECM, further demonstrating this important interplay between platelets and immune responses in cerebral malaria." (PMID 20454664, 2010). "In other experiments, injections of leptin were claimed to protect against TNF toxicity in ob/ob but not in +/+ mice; therefore, it is possible that leptin protects against cerebral malaria by damping down TNF-induced pathology." (PMID 18489748, 2008). "Moreover, the composition of EVs in late-stage disease points to specific pathogenic processes: gene sets related to platelet activation, TNF and VEGF signaling, neurotrophin signaling, and glutamatergic neurotransmission are enriched in EVs from patients with advanced cerebral malaria." (PMID 41002937, 2025). "Targeting immune molecules such as TNF-α during cerebral malaria have not improved clinical outcomes, suggesting that there is a need to understand more about the role of different immune molecules during CM, to effectively target them for therapeutic purposes." (PMID 35222377, 2022). "Not until 8 years ago was the excess TNF in cerebral malaria shown to originate in the brain." (PMID 27596607, 2016). "Higher TNF-α was also reported in fatal compared to nonfatal cerebral malaria in African children." (PMID 24669217, 2014). "Importantly, LTα, not TNF, has been shown to be a critical factor in the development of experimental cerebral malaria in C57BL/6 mice, identifying LTA along with TNF as a candidate susceptibility gene." (PMID 21029472, 2010). "Additionally, lack of TNF receptor 2 conferred resistance to cerebral malaria in mice, thought to be due to blocking the upregulatory effects of TNF on ICAM-1 expression in brain microvascular endothelial cells." (PMID 19680452, 2009). "Serum TNF, IFN-γ, IL-1β, IL-6, and IL-10 did not vary based on either TLR2 Δ22 or GTn genotype in children with cerebral malaria." (PMID 22336003, 2012).
cerebral malaria (continued). "SMA is associated with elevated levels of myelo-suppressive cytokines, such as TNF, but this is not specific to the SMA syndrome, as children with cerebral malaria (CM) also have highly elevated TNF plasma levels." (PMID 22853732, 2012). "Although these studies were performed with cerebral malaria and not MA-ARDS, they suggest that blocking TNF pathways may not be the best option to promote recovery from MA-ARDS." (PMID 38236930, 2024).
E. coli infection (111 papers, 2008 to 2026). "KEGG pathway enrichment analysis results showed that the co-significant DEGs were mainly enriched in the TNF signaling pathway, pathogenic escherichia coli infection, and the regulation of actin cytoskeleton." (PMID 39290984, 2024). "For the “Pathogenic Escherichia coli infection” pathway, the study recognized some important inflammatory factors, such as TNF-α, IL‐1β, IL‐1, IL‐8, and NF‐κb, which were associated with different signaling pathways." (PMID 36798127, 2023). "For the “pathogenic E. coli infection” signal pathway, some inflammatory factors that affect the process of AS, such as TNF α, IL-1 β, IL-1, IL-8 as well as NF-κB, are associated with this signal pathway." (PMID 36798127, 2023). "Meanwhile, KEGG analysis showed that these genes were enriched mainly in TNF signaling pathway, pathogenic Escherichia coli infection, IBD and tight junction." (PMID 37016023, 2023). "Meanwhile, KEGG revealed the TNF signaling pathway, Pathogenic Escherichia coli infection, IBD, and TJ associated with these genes." (PMID 37016023, 2023). "By detecting the mRNA levels of multiple cytokines in macrophages, we found that E. coli infection caused a sharp increase in the expression of Il-1β, TNF-α." (PMID 37644526, 2023). "KEGG pathway analysis demonstrated the gene set was enriched in DNA replication, steroid biosynthesis, ACE-RAGE signaling, TNF signaling, and pathogenic E Coli infection." (PMID 36229484, 2022). "Studies have confirmed that the mRNA expression of TNF-α, IL-6, IL-8, and other cytokine genes was increased in intestinal tissues of weaned piglets caused by E. coli infection." (PMID 35571917, 2022). "IFN-γ and TNF-α treatment in combination with C. rodentium and pathogenic E. coli infection negatively affected mucus parameters in vitro, which was relieved by IL-4 treatment." (PMID 30665337, 2019). "E. coli infection caused an acute suppurative inflammation in the lung with increased lung index and serum TG and TC contents; elevated pulmonary tumor necrosis factor-α, interleukin (IL)-1β, IL-6, IL-8, and leptin levels; and oxidative stress in mice." (PMID 30250258, 2018). "Previous studies have shown that taking BBR can significantly alleviate the increase in serum IL-6, IL-1β, and TNF-α caused by Escherichia coli infection in chicks and alleviate the increase in IL-6, IL-8, and TNF-α expression in the intestine caused by Escherichia coli infection in weaned piglets." (PMID 40829428, 2025). "The results of the current study showed that nicotinic acid supplements in the diet could ameliorate inflammation by down-regulated the expression of TNF-α, IL-6, and IL-8 in piglets caused by E. coli infection." (PMID 35571917, 2022). "Clinically source MDR E. coli strains infection caused serious systemic inflammatory response by sharply increasing the serum proinflammatory cytokines, such as TNF-α, IFN-γ, IL-6 (P < 0.05), and a significant reduction in IL-4 levels (P < 0.05) compared with the control group." (PMID 35250983, 2022). "Therefore, we hypothesize that the increase in EGFR might be caused by E. coli infection and subsequent TNF-α release, thereby amplifying AREG function." (PMID 30524196, 2018). "Differently, the levels of the inflammatory cytokine TNF-α were significantly reduced in BL-primed cells in response to E. coli infection, reaching levels similar to those secreted by the untreated cells." (PMID 40384982, 2025). "Concurrently, increased p-RIPK3 levels were also detected in pulmonary BALF cells after E. coli infection (including L929 cells treated with TNF-⍺ and Z-VAD as a positive control of p-RIPK3)." (PMID 40359428, 2025). "We observed that 24 h of PGD2 pretreatment followed by 6 h of E. coli infection increased pro-inflammatory cytokines (TNF-α, IL-1β, and IL-8) secretion in BMDMs." (PMID 40874199, 2025).
E. coli infection (continued). "Our results showed that E. coli infection triggered both a strong inflammatory response, via NF-κB pathway activation and pro-inflammatory cytokine (TNF-α, IL-6, IL-1β) release, and apoptotic cell death." (PMID 41302013, 2025). "L. fermentum MC018 reduced the levels of IL-1β, IL-6, and TNF-α in intestinal tissues following E. coli infection." (PMID 40963585, 2025). "After 9 h, PGD2 treatment significantly increased TNF-α, IL-1β, IL-6, and IL-8 levels compared to the E. coli infection group, while IL-10 levels decreased." (PMID 40874199, 2025). "In contrast, E. coli infection in normoxia (NE) mildly activates hypoxia, glycolysis, Hedgehog signaling, TNFα signaling via NFκB, IL2 STAT5 signaling, and Notch signaling." (PMID 38720110, 2024). "In studies where piglets were challenged by lipopolysaccharide, or Escherichia coli infections, in-feed fucoidan supplementation was shown to enhance piglet immune responses by upregulating pro-inflammatory cytokines, including intestinal TNF-α." (PMID 38791689, 2024). "In this study, E. coli infection resulted in elevated levels of TNF-α, IL-1β, and IL-6, accompanied by decreased IL-10 levels in the JM group, consistent with findings in animals induced with bacterial and Lipopolysaccharide challenges." (PMID 39199953, 2024). "After E. coli infection, the expression levels of inflammatory cytokines TNF-α, IL-8, and IFN-γ increased significantly (P < 0.05)." (PMID 39600797, 2024). "The levels of IL-6, IL-8, and TNF-α expression in the endometrium of dairy cows were elevated 48 h post E. coli infection." (PMID 39409825, 2024). "In the validation set, compared to the other bacterial infection groups, we discovered that the E. coli infection group had a greater TNF level (p < 0.05), while the HSPA1B level was diminished in comparison to the other bacterial groups (p < 0.01)." (PMID 38066783, 2023). "Based on DEGs, WGCNA, and MCODE, key genes associated with E. coli infection were discovered, including CXCL3, HSPA1B, TNF, and PLPP3." (PMID 38066783, 2023). "To determine why U2AF1-S34F mice succumbed to E. coli infection, we monitored the production of the pro-inflammatory cytokines TNFα and IL-6 in the peritoneum and blood after peritoneal E. coli infection." (PMID 37591942, 2023). "From the review of existing research, the F18+ E. coli infection triggers intestinal inflammation, resulting in elevated IL6 (60%), IL8 (43%), and TNF-α (28%), increasing oxidative damages, and causing a 14% reduction in villus height." (PMID 37685055, 2023). "The TNF level of the clinical E. coli infection group was also slightly lower than that of the Gram-positive bacterial infection group, but the difference was not significant (p = 0.332)." (PMID 38066783, 2023). "The KEGG analysis showed that the genes were enriched in cytokine and cytokine receptor, interleukin (IL)-17 signaling pathway, tumor necrosis factor (TNF) signaling pathway, pathogenic Escherichia coli infection, and complement and coagulation cascades." (PMID 36468038, 2022). "Dietary MOS supplementation significantly reduced TNF-α in broiler serum under HS condition, reduced oxidative stress and inflammatory response due to Escherichia coli infection, and significantly reduced TNF-α and NF-κB mRNA expression in liver tissue." (PMID 35681861, 2022). "Specifically, in vitro, pretreatment with MLA (50 μM) or MEM (50 μM) significantly attenuated the survival rates of HBMECs and reduced the expression of inflammatory cytokines (such as IL-6 and TNF-α) after E. coli infection." (PMID 36289622, 2022). "As expected, the levels of IL-6, TNF-α, IL-10, and the neutrophil chemoattractant keratinocyte-derived chemokine (KC) were increased in the sera of virgin control mice after E. coli infection." (PMID 33622714, 2021). "Up-regulation of interleukin (Il)-1β, Il-6, Il-8, Il-18, tumor necrosis factor alpha, and chemokine Cxcl2 expression after E. coli infection was attenuated by L. johnsonii L531." (PMID 32823867, 2020).
E. coli infection (continued). "Previous studies have shown that the release of these cytokines, such as TNF-α, IL-6, and IL-1β, was induced by LPS during Escherichia coli infection." (PMID 33134350, 2020). "In this study, SeMet inhibited E. coli-induced protein expression of TNF-α and IL-1β, indicating that SeMet suppressed inflammation induced by E. coli infection in bMECs and macrophages and inhibited the cytokine storm." (PMID 32733409, 2020). "Together with TNF or NF data, agrimos® can apparently regulate the cytokine responses of broiler chicks with E. coli infection, and its immunomodulatory effects seem to be protective by repressing the ongoing inflammation." (PMID 32560684, 2020). "On the other hand, agrimos® reduced oxidative stress and slowed down inflammation that occurs as a result of E. coli infection through decreased TNF and NF expressions in liver tissue." (PMID 32560684, 2020). "As reported in our previous study, after E. coli infection, there were continuous increases of the pulmonary cytokine levels, especially TNF-α and IL-8, and oxidative stress levels in the lean-and DIO-E." (PMID 32685099, 2020). "Both addition of TNF and E. coli infection strongly up-regulated memCD95L on PBMO and to a lesser degree in CBMO (compare groups 2 and 3)." (PMID 30897723, 2019). "The knockdown of duNLRP3 significantly impaired the mRNA expression levels of IL-1β, IL-18, and TNF-α induced by E. coli infection (P < 0.01)." (PMID 30349536, 2018). "We also detected the mRNA expression levels of inflammatory cytokines IL-1β, IL-18, and TNF-α in the liver, spleen, and brain after the E. coli infection." (PMID 30349536, 2018). "Instead, the increased blood triglyceride content is probably due to increased catabolism of adipose and muscle tissues, as TNF-α produced following E. coli infection has been shown to suppress lipogenesis and enhance lipolysis in these tissues." (PMID 30563203, 2018). "In this study, we demonstrated the role of duNLRP3 in the expression of inflammatory cytokines IL-1β, IL-18, and TNF-α mRNA after E. coli infection." (PMID 30349536, 2018). "E. coli infection markedly increased the mRNA levels of IL-6 and TNF-α, but such increases were prevented by the C. militaris mycelium producing Mag II-CB." (PMID 29402269, 2018). "Upon E. coli infection in mice, the host rapidly induces an efficient protective program that involves mammary NF-kappaB transcription to enhance TNF-alpha (E. coli mediated immune response)." (PMID 25162221, 2014). "In in vitro culture, TNF-α plays a central role to regulate the other cytokines especially IL-17 and IL-12 that are rapidly generated in bacterial E. coli infection." (PMID 25120287, 2014). "In this study, we examined the effect of E. coli infection on the expression of the pro-inflammatory cytokines IL-1β, IL-6, and TNF-α in PRNP-knockout macrophages." (PMID 25058617, 2014). "However, at 12 and 24 h post-infection, PGD2 significantly downregulated the secretion of TNF-α, IL-1β, and IL-8 compared to the E. coli infection group, while the secretion of IL-6 and IL-10 remained elevated (P < 0.01)." (PMID 40874199, 2025). "E. coli infection increased IL-1β and TNF-α levels in the jejunum of broilers." (PMID 40963585, 2025). "The previous observations and results prompted us to investigate whether E. coli infection also affected the production of TNF-α in the cells of the intestinal mucosa." (PMID 39627566, 2024). "Remarkably, the double challenge of high glucose and infection provoked a pathogen-specific attenuated placental inflammatory response in the hyperglycemic condition, mainly denoted by reduced TNF-α and IL-6 secretion after S. agalactiae infection and by IL-1β after E. coli infection." (PMID 36982317, 2023). "Furthermore, the attenuated inflammatory response in hyperglycemic placenta was pathogen-specific, with the suppression of TNF-α and IL-6 or IL-1β after S. agalactiae and E. coli infection, respectively." (PMID 36982317, 2023).